XBP1 (X-box binding protein 1)
Diseases named in the same sentence as XBP1 in open-access papers (continued):
Sharing a sentence is not in itself a finding about the gene and the disease.
Dengue virus infection (1 paper, 2007). "In Dengue infected cells, the spliced form of XBP1 mRNA (sXBP1) was detected 48 h post-infection as well as in our positive control with TG." (PMID 17888185, 2007). "The level of XBP1 mRNA significantly increased in Dengue-infected cells at 24 h post-infection." (PMID 17888185, 2007). "Furthermore, it was also reported that the XBP1 downstream genes such as EDEM1 and p58 (IPK) were induced in Dengue infected cells." (PMID 17888185, 2007). "We find that upon Dengue virus infection, A549 cells elicit an UPR which is observed at the level of translation attenuation (as visualized by the phosphorylation of eIF2alpha) and activation of specific pathways such as nuclear translocation of ATF-6 and splicing of XBP-1." (PMID 17888185, 2007).
development (1 paper, 2021). "In this study, our data confirm that hyperandrogen induced ovarian GC apoptosis in PCOS-like rats, which was mediated by excessive ER stress and IRE1α-XBP1 pathway activation, resulting in follicle development disorders." (PMID 34987702, 2021).
dilated cardiomyopathy (1 paper, 2015). Cardiomyopathy which is characterized by dilation and contractile dysfunction of the left and right ventricles. "Cardiac angiogenic imbalance leads to dilated cardiomyopathy, so spliced XBP1 may presents its cardioprotection against prolonged cardiac stress by promoting VEGF mediated-cardiac angiogenesis." (PMID 26572862, 2015).
embryonic carcinoma (1 paper, 2024). "➢ATRA (10–20 μM) induced splicing of XBP1 mRNA in 1 h in HuH-7 cells.➢ATRA (10–20 μM) induced accumulation of XBP1 protein in the nucleus of HuH-7 cells in 8 h.✧In P19 embryonic carcinoma cells, ATRA induced the upregulation of several UPR-related genes (Atf6, Xbp1, Chop)." (PMID 38786033, 2024).
endocarditis (1 paper, 2024). Inflammation of the endocardium. "In Phenome-wide MR Analysis, XBP1 was shown to play a role in the risk of endocarditis, and considering that the correlation between AF and infective endocarditis has been pointed out, we hypothesized that this may be one of the mechanisms by which XBP1 causes the development of AF." (PMID 39170695, 2024).
endophthalmitis (1 paper, 2022). An infectious process affecting the internal structures of the eye. "Kumar reported that the IRE1/XBP-1 pathway regulated the retinal innate immune response in S. aureus-induced endophthalmitis." (PMID 35327108, 2022).
enterovirus infection (1 paper, 2022). "We concluded that even though Ire1 is phosphorylated at the middle and later stages of enterovirus infection, its activity in Xbp1 mRNA splicing is simultaneously inhibited in the infected cells in a virus-dependent manner." (PMID 36366584, 2022).
eosinophilic leukemia (1 paper, 2021). "Finally, blockade of eosinophilic leukemia maturation by ablating Gata1 or Xbp1 prevents relapse in a significant proportion of mice." (PMID 34764270, 2021).
epilepsy (1 paper, 2024). A brain disorder characterized by episodes of abnormally increased neuronal discharge resulting in transient episodes of sensory or motor neurological dysfunction, or psychic dysfunction. "Alterations in XBP1 expression are implicated in neurological disorders including epilepsy." (PMID 39596674, 2024).
esophagitis (1 paper, 2023). An acute or chronic inflammatory disease affecting the esophageal wall. "ATF-6, XBP-1, DNAJC-9, and NF-2-L-2 levels were significantly decreased after treatment in patients without esophagitis in the endoscopic examination." (PMID 37158535, 2023).
Francisella tularensis infection (1 paper, 2019). "The relevance of XBP1 in the control of infection was underscored in a model of Francisella tularensis infection, where selective deletion of XBP1 in macrophages resulted in enhanced pathogen burden." (PMID 31817075, 2019).
gallstones (1 paper, 2020). Solid crystalline precipitates in the biliary tract, usually formed in the gallbladder, resulting in the condition of cholelithiasis. "The expression of XBP1 and NAT1 was non-significantly associated with the occurrence of gallstone in AC (all P > 0.05)." (PMID 32793479, 2020). "The expression of XBP1 was non-significantly related to the occurrence of gallstone in SC/ASC (P = 0.104)." (PMID 32793479, 2020). "The expression of XBP1 and NAT1 was non-significantly related to the occurrence of gallstone in GBC (all P > 0.05)." (PMID 32793479, 2020). "Additionally, we found that other clinicopathological features, including tumor differentiated degree, tumor size, the occurrence of gallstone, TNM stages, and XBP1 and NAT1 expression were non-significantly different in SC/ASC and AC." (PMID 32793479, 2020).
glomerulosclerosis (1 paper, 2021). A hardening of the kidney glomerulus caused by scarring of the blood vessels. "Somlo and colleagues reported that site-specific deficiency of XBP1 in podocytes resulted in severe albuminuria, glomerulosclerosis, and kidney fibrosis in a Sec63 and XBP1 double knockout model." (PMID 34445377, 2021).
HCMV infection (1 paper, 2013). "In concordance with the previous reports that activated IRE1α catalyzes the non-conventional splicing of the mRNA encoding X-box binding protein 1 (XBP1), the spliced XBP1 mRNA increased gradually after HCMV infection in NSPC/iPSCs." (PMID 24144363, 2013).
Hepatitis C (1 paper, 2013). "Other examples of XBP1 splicing-downstream target disconnection come from the viral literature, and Hepatitis C in particular." (PMID 24339776, 2013).
herpesvirus infection (1 paper, 2024). "They found herpesvirus proteins in AECs from 15/23 IPF patients, which colocalized with UPR marker XBP-1 (X-box binding protein-1), indicating a potential link between herpesvirus infection, ER stress, and IPF progression." (PMID 39760094, 2024).
homocystinuria (1 paper, 2016). An autosomal recessive inherited metabolic disorder caused by mutations in the CBS, MTHFR, MTR, and MTRR genes. "To investigate ER stress in homocystinuria patients with remethylation defects, we have analysed the expression of genes involved in UPR (Grp78, PERK, XBP1, ATF4 and CHOP) and Ca2+ homeostasis (Herp and IP3R1) at protein or mRNA levels in controls and patients-derived fibroblasts." (PMID 26959487, 2016).
Hypercholesterolemia (1 paper, 2023). An increased concentration of cholesterol in the blood. "Moreover, we showed that capsaicin alleviates the rates of atherosclerotic lesions in diet-induced hypercholesterolemia by inhibiting the expression of ER stress proteins like eIF2α, XBP-1, CHOP, and GRP78." (PMID 38084147, 2023).
hypertriglyceridemia (1 paper, 2022). A laboratory test result indicating elevated triglyceride concentration in the blood. "Our preliminary results demonstrate that metformin activates AMPK to reduce TG synthesis by inhibiting the XBP1-mediated DGAT2 pathway, at least in part, suggesting that XBP1 is a new metabolic mediator for metformin treatment of hypertriglyceridemia and associated metabolic diseases." (PMID 36438823, 2022). "Our preliminary results demonstrate that metformin activates AMPK to reduce TG synthesis by inhibiting the XBP1-mediated DGAT2 pathway, at least in part, suggesting that XBP1 is a new metabolic mediator for metformin treatment of hypertriglyceridemia and associated metabolic disease." (PMID 36438823, 2022). "Therefore, the present study investigated whether metformin improves hypertriglyceridemia via regulation of DGAT2 or XBP1 in the liver and whether AMPK is involved." (PMID 36438823, 2022). "The present study aim to investigate the molecular mechanism by which metformin improves hypertriglyceridemia via regulation of diacylglycerol O-acyltransferase 2 (DGAT2) and X-box binding protein 1 (XBP1) in the liver and whether AMP-activated protein kinase (AMPK) is involved." (PMID 36438823, 2022).
Hypoglycemia (1 paper, 2025). A decreased concentration of glucose in the blood. "We recently showed that 5 h hypoglycemia in mice also induces ER stress (X-box binding protein 1 splicing) in many retinal cells, including the RGC layer." (PMID 41294828, 2025).
inclusion body myositis (1 paper, 2018). A slowly progressive degenerative inflammatory disorder of skeletal muscles characterized by late onset weakness of specific muscles and distinctive histopathological features. "ER-stress and the activation of the unfolded proteins response (UPR), as the respective cellular defence mechanism, have been described in sporadic inclusion-body myositis (sIBM), In contrast, UPR key players (ATF4, ATF6, BiP and XBP1) in muscle of GNE patients lacked any evidence of UPR induction." (PMID 29720219, 2018).
intestinal infection (1 paper, 2024). "Since fewer ILC3s from Ire1αΔRorc mice produced protective cytokines, we assessed the functional relevance of IRE1α/XBP1 deficiency in ILC3s in models of intestinal infection that cause barrier damage and activate ILC3s." (PMID 38722686, 2024).
intestinal tumor (1 paper, 2025). "In earlier studies, we have shown that Xbp1/Rnaseh2bΔIEC exhibit increased intestinal epithelial DNA damage as well as increased stem cell proliferation compared to Rnaseh2bΔIEC mice, and 48% of these mice develop intestinal tumor,s which are largely adenocarcinomas." (PMID 41057521, 2025). "Furthermore, we examined whether the functioning interplay between ATG16L1 and XBP1, which is known to contribute to sporadic Crohn-like enteritis in mouse models of IBD, might be involved in transcription-associated mutagenesis and the manifestation of intestinal tumors." (PMID 41057521, 2025).
intracerebral hemorrhage (1 paper, 2023). A cerebrovascular disorder characterized by bleeding into one or both cerebral hemispheres including the basal ganglia and the cerebral cortex. "Although CDNF was shown to regulate UPR initiated by transducers IRE1α, PERK and ATF6 in the pathological condition, we found that mRNA levels of UPR markers Grp78, spliced Xbp1, Atf4, and Chop were not significantly different between WT and Cdnf−/− mice after intracerebral hemorrhage." (PMID 36792604, 2023).
limb ischemia (1 paper, 2010). A ischemia that involves the limb. "Taurine pretreatment downregulated the expression of XBP-1, ATF4, and CHOP mRNA in lung tissues following limb ischemia reperfusion (M-W test, p = 0.017, p = 0.04, and p = 0.03, respectively)." (PMID 20148646, 2010).
lipid metabolic disorders (1 paper, 2016). "In our experiment, we determined that the IRE1α/XBP-1 branch was the major pathway involved in stimulating ER stress, leading to the lipid metabolic disorders in SCH." (PMID 27539723, 2016).
liver cirrhosis (1 paper, 2018). "Wu et al68 have demonstrated that during end-stage liver cirrhosis in mice, hepatic Nrf2 is suppressed as a consequence of activation of the Ire1α-Xbp1 arm of the UPR, thereby exacerbating oxidative stress and promoting further disease." (PMID 29552625, 2018).
lymphedema (1 paper, 2025). Excess fluid collection in tissues, causing swelling. "We evaluated ER stress markers spliced X-box binding protein 1 (sXBP-1) and C/EBP homologous protein (CHOP) in mice with lymphedema fed the HSFD, as lipotoxicity can induce ER stress." (PMID 40759794, 2025).
mesenchymal tumors (1 paper, 2018). "This was also confirmed by the fact that the XBP1+/RIDD− population was enriched in mesenchymal tumors whereas XBP1−/RIDD+ comprised more pro‐neural and neural tumors." (PMID 29311133, 2018).
metastatic tumor (1 paper, 2021). "In particular, XBP-1 was expressed at high levels in metastatic tumor samples of patients with CRC, and in vitro studies revealed that overexpression of XBP-1 promoted CRC cell invasion, while inhibition of XBP-1 significantly suppressed cell invasion." (PMID 34521445, 2021).
multiple sclerosis (1 paper, 2013). A progressive autoimmune disorder affecting the central nervous system resulting in demyelination. "Our and other studies have demonstrated upregulation of ER stress markers CHOP, BiP, ATF4, XBP1 and phosphorylated e-IF2 alpha (p-eIF2 alpha) in biopsy and post-mortem human multiple sclerosis (MS) samples." (PMID 24252779, 2013).
myeloid leukemia (1 paper, 2016). A clonal proliferation of myeloid cells and their precursors in the bone marrow, peripheral blood, and spleen. "Following TM treatment, increased expression of XBP1s mRNA and decreased XBP1u (unspliced, transcriptional inactive form of XBP1) were observed in 293T and K562 myeloid leukemia cells." (PMID 26934650, 2016).
myeloproliferative neoplasm (1 paper, 2026). A clonal hematopoietic stem cell disorder, characterized by proliferation in the bone marrow of one or more of the myeloid (i.e., granulocytic, erythroid, megakaryocytic, and mast cell) lineages. "Type I CALR mutations, but not type II, activate the inositol-requiring enzyme 1α (IRE1α)/X-box binding protein 1 (XBP1) pathway of the unfolded protein response, driving the development of myeloproliferative neoplasms." (PMID 41262532, 2026).
Myocardial fibrosis (1 paper, 2024). "Therefore, the role of spliced XBP1 (the active form of XBP1) in promoting myocardial fibrosis may be one of the mechanisms underlying the development of AF." (PMID 39170695, 2024).
necrotizing enterocolitis (1 paper, 2018). Necrotizing enterocolitis (NEC) is a devastating disease that affects mostly the intestine of premature infants. "For example, in human necrotizing enterocolitis, XBP1 splicing levels correlate with the severity of mucosal damage that is associated with increased mucosal expression of pro-inflammatory cytokines, IL-6 and IL-848." (PMID 29891850, 2018).
Neurodegeneration (1 paper, 2018). Progressive loss of neural cells and tissue. "Our findings suggest that the absence of XBP1, a critical component of the UPR, accelerates age-related retinal neurodegeneration." (PMID 29615095, 2018).
neuropathy (1 paper, 2020). A disorder affecting the nervous system that manifests with pain, tingling, numbness, and/or muscle weakness. "Another study observed links between aminoglycoside-induced mistranslation and protein misfolding on the one hand, and neuropathy in XBP1-haploinsufficient (XBP1+/−) mice." (PMID 32527008, 2020).
non-alcoholic fatty liver disease (1 paper, 2024). "Within the biological process of non-alcoholic fatty liver disease, dietary supplementation with PPAH increased the expression of the Lep and Xbp1 genes." (PMID 39591294, 2024).
osteoporosis (1 paper, 2025). A condition of reduced bone mass, with decreased cortical thickness and a decrease in the number and size of the trabeculae of cancellous bone (but normal chemical composition), resulting in increased fracture incidence. "Notably, chaperone protein BIP upregulation ameliorates bone loss in osteoporosis models, underscoring XBP1’s role in maintaining osteoblast viability under stress." (PMID 41301756, 2025). "This mechanistic understanding provides a foundation for developing XBP1-targeted therapies to accelerate fracture healing and treat osteoporosis." (PMID 41301756, 2025).
otitis (1 paper, 2021). "The levels of expression of BLIMP-1 and XBP1 were significantly lower in patients who were prone than those who were not prone to otitis, whereas expression of BCL6 and PAX5 tended to be higher in the otitis-prone group." (PMID 33801155, 2021).
otitis media (1 paper, 2021). Inflammation of the anatomical structures of the middle ear, which is most often caused by an infectious process. "B cell leukemia/lymphoma-6 (Bcl-6) and paired box gene 5 (Pax-5) suppress antibody production, whereas B lymphocyte inducer of maturation program 1 (Blimp-1) and X-box binding protein 1 (XBP-1) promote antibody production during immune responses in patients with otitis media." (PMID 33801155, 2021).
ovarian hyperstimulation syndrome (1 paper, 2017). A complication of ovulation induction in infertility treatment. "Recent studies have shown a positive correlation between spliced XBP1 (induced by ER stress) and ovarian hyperstimulation syndrome (OHSS), a major complication during infertility treatment that is mainly characterized by increased capillary permeability." (PMID 27638465, 2017).
ovary diseases (1 paper, 2021). "Moreover, several studies have shown that XBP1 displays a role in the pathological aspect of ovary diseases." (PMID 34121978, 2021).
pancreatic ductal adenocarcinoma (1 paper, 2021). An infiltrating adenocarcinoma that arises from the epithelial cells of the pancreas. "In addition, genetic mouse models have unequivocally shown that Xbp1 is required for acinar homeostasis and pancreatic ductal adenocarcinoma, the most common form of PC, can be initiated from acinar cells." (PMID 33517887, 2021).
pemphigus (1 paper, 2025). Pemphigus is a group of rare autoimmune diseases that cause blistering of the skin and mucous membranes (mouth, nose, throat, eyes, and genitals).This conditioncan occur at any age, but often strikes people in middle or older age. "To enhance clinical decision-making, we developed a nomogram model that integrates the expression scores of ACSL4, SAT2, and XBP1 for predicting the risk of pemphigus." (PMID 40612574, 2025). "We also developed a nomogram model integrating the expression scores of ACSL4, SAT2, and XBP1 to predict pemphigus risk, which showed good calibration and significant clinical utility." (PMID 40612574, 2025). "Collectively, these findings indicate that ACSL4, SAT2, and XBP1 exhibit consistent and significant diagnostic value, supporting their candidacy as promising diagnostic biomarkers for pemphigus." (PMID 40612574, 2025). "Results revealed that SAT2 and XBP1 were up-regulated in the pemphigus group compared to the control group, whereas ACSL4 expression was reduced in the pemphigus group." (PMID 40612574, 2025). "The results showed that SAT2 (p = 0.0079) and XBP1 (p = 0.0004) had significantly higher expression levels in the pemphigus group compared to the control group." (PMID 40612574, 2025). "Differential expression analysis was conducted to investigate the expression patterns of the five genes (XBP1, FBXO45, SAT2, AIFM1, and ACSL4) and eight other DEGs associated with ferroptosis (G3BP1, WBP11, TET2, IRF8, FASN, GDPD5, H1-4, and HUWE1) in both the pemphigus and control groups." (PMID 40612574, 2025).
Peri-Implantitis (1 paper, 2024). An inflammatory process with loss of supporting bone in the tissues surrounding functioning DENTAL IMPLANTS. "PERK expression exceeded XBP1 significantly in FFF hyperplastic tissue, while expression levels of PERK, XBP1, and ATF6 were not significantly different in peri-implantitis and FBG tissues." (PMID 38730018, 2024).
pituitary tumor (1 paper, 2020). A benign or malignant neoplasm affecting the pituitary gland. "The ER interaction may deserve special attention, given our observation that overexpression of XBP1, an activator of ER biogenesis, is sufficient to cause global 3ʹUTR shortening in the pituitary tumor cell line AtT-20." (PMID 32576858, 2020). "To this end, we analyzed an RNA-seq dataset involving overexpression (OE) of active forms of XBP1 (spliced form) and Creb3l2 (cleaved form) in the mouse pituitary tumor cell line AtT-2045." (PMID 32576858, 2020).
plasma cell neoplasm (1 paper, 2018). A clonal proliferation of immunoglobulin-secreting plasma cells. "Cells of the plasma cell neoplasm, MM, are dependent on a functioning IRE1α/XBP1 arm of the UPR." (PMID 29423023, 2018).
polycystic ovary syndrome (1 paper, 2022). A disorder that manifests as multiple cysts on the ovaries. "Furthermore, polycystic ovary syndrome (PCOS) patients have been reported to have reduced XBP-1 mRNA expression after resveratrol treatment, which is in line with our findings." (PMID 36175937, 2022).
prediabetes (1 paper, 2019). "In LOsG-induced prediabetes, although pancreatic ROS stress remained high on LOsG treatment day 38, there were no alterations in mRNA levels of ER stress (XBP1 and BIP), inflammation (IL6 and IL1β), and hypoxia-responsive (HIF1α and GAPDH) genes between LOsG- and sham-treated groups." (PMID 30975975, 2019).